TNNI1 (troponin I1, slow skeletal type)
Description:
Troponin I is the inhibitory subunit of troponin, the thin filament regulatory complex which confers calcium-sensitivity to striated muscle actomyosin ATPase activity.
Synonyms: ssTnI; TNN1
Tractability: No criterion of Open Targets' tractability assessment is met for any kind of drug.
Gene: Protein-coding gene on chromosome 1 (201,403,784 to 201,429,866, reverse strand). Ensembl gene ENSG00000159173.
Subcellular location (Human Protein Atlas): Nucleoplasm; Nucleoli
Pathways (Reactome):
Muscle contraction: Striated Muscle Contraction
Gene Ontology:
Molecular function: protein binding
Biological process: cardiac muscle contraction; regulation of striated muscle contraction; skeletal muscle contraction
Cellular component: cytosol; troponin complex
Genetic constraint (gnomAD): Loss-of-function variants: 14 observed, 25.24 expected, observed/expected ratio (o/e) 0.55, 90% interval 0.37 to 0.87. The upper end of that interval is the gene's LOEUF score, 0.87, which puts it in group 3 of 6, group 1 being the genes least tolerant of losing a copy. Missense variants: 164 observed, 263.54 expected, observed/expected ratio (o/e) 0.62, 90% interval 0.55 to 0.71. Synonymous variants: 79 observed, 101.11 expected, observed/expected ratio (o/e) 0.78, 90% interval 0.65 to 0.94.
Gene-disease validity (ClinGen):
ClinGen rates the evidence that TNNI1 causes each of these diseases.
childhood-onset nemaline myopathy (autosomal recessive): Limited. Childhood onset nemaline myopathy, or mild nemaline myopathy is a type of nemaline myopathy (NM) characterized by distal muscle weakness, and sometimes slowness of muscle contraction.
nemaline myopathy (autosomal dominant): Limited. Nemaline myopathy (NM) encompasses a large spectrum of myopathies characterized by hypotonia, weakness and depressed or absent deep tendon reflexes, with pathologic evidence of nemaline bodies (rods) on muscle biopsy.
Homologues: Orthologues: chimpanzee TNNI1 (100% identical), macaque TNNI1 (99% identical), mouse Tnni1 (98% identical), rabbit TNNI1 (98% identical), guinea pig TNNI1 (97% identical), pig TNNI1 (97% identical), rat Tnni1 (96% identical), tropical clawed frog tnni1 (79% identical), zebrafish tnni1b (76% identical), zebrafish tnni1a (74% identical), dog TNNI1 (71% identical), Caenorhabditis elegans unc-27 (32% identical), and 4 more. Paralogues in human: TNNI3 (59% identical), TNNI2 (55% identical).
Diseases named in the same sentence as TNNI1 in open-access papers:
TNNI1 is named in the same sentence as 18 diseases in open-access papers, as found by Europe PMC text mining. Sharing a sentence is not in itself a finding about the gene and the disease. The quoted sentences say what the papers report.
non-small cell lung carcinoma (2 papers, 2016 to 2018). A group of at least three distinct histological types of lung cancer, including non-small cell squamous cell carcinoma, adenocarcinoma, and large cell carcinoma. "In another study, down-regulation of the TNNI1 gene quelled proliferation of human non-small-cell lung carcinoma xenografts in mice." (PMID 29416706, 2018). "For this purpose, we used the human non-small cell lung carcinoma line A549, which expresses high levels of TNNI1, and a shRNA construct that allows expression concomitant with red fluorescent protein (RFP) upon induction by doxycycline feeding." (PMID 27437768, 2016). "Since it was previously shown that knockdown of TNNI1 in a mouse model bearing non-small-cell lung carcinoma xenografts restrained cell proliferation, it would be worthwhile to determine if targeted knockdown of TNNI1 in certain cancers thwarts tumor growth and metastasis in larger animals models." (PMID 29416706, 2018).
breast carcinoma (1 paper, 2020). "TNNI1, a gene that is shared by both this model and PE‐Ima, is one of the three inhibitory subunits of smooth muscle troponin that are all overexpressed in breast cancer." (PMID 34766125, 2020).
chronic myelogenous leukaemia (1 paper, 2020). "PE‐Ima (LIF, MRGPRF, GRM3, TNNI1 and CACNA2D1) predicted imatinib response in chronic myelogenous leukaemia patients." (PMID 34766125, 2020).
heart failure (1 paper, 2014). Inability of the heart to pump blood at an adequate rate to meet tissue metabolic requirements. "At the level of the cardiac sarcomere, as cTnI (TNNI3 gene product) progressively replaces ssTnI (TNNI1) during maturation, there is no reactivation of the fetal TNNI1 gene program, even in disease states including stress, hypertrophy (physiological or maladaptive), ischemia, or in heart failure." (PMID 25358788, 2014).
Sepsis (1 paper, 2024). Sepsis is defined as life-threatening organ dysfunction caused by a dysregulated host response to infection. "Together, these results imply that the downregulation of key proteins associated with slow‐twitch skeletal muscle, such as Mb, Tnni1, and Myh7, may contribute to aggravating muscle weakness and wet weight reduction in WT, compared with PD‐1‐KO, sepsis survivor mice." (PMID 39016179, 2024). "Our finding indicating that IL‐13 restores the sepsis‐induced decrease in expression of Mb, Tnni1, and Myh7 at the transcriptional level would support the potential roles of IL‐13 in improving or preserving muscle atrophy and weakness in sepsis." (PMID 39016179, 2024). "Similar to those in skeletal muscles of sepsis mice, expression of Mb, Tnni1, and Myh7 mRNAs was downregulated, while that of IL‐13RA1 was upregulated in LPS‐stimulated C2C12 myotubes." (PMID 39016179, 2024). "Tnni1 and Myh7 directly regulate muscle contraction and decreased expression of these proteins may be involved in muscle weakness in sepsis." (PMID 39016179, 2024).
valvular heart disease (1 paper, 2024). "In human patients with valvular heart disease, the expression of troponin I type 1 (TNNI1) is inhibited or inactivated." (PMID 38892128, 2024).
cancer (5 papers, 2016 to 2022). A tumor composed of atypical neoplastic, often pleomorphic cells that invade other tissues. "The study reported that the potential muscle-specific genes expressed in cancer cells were TNNI1, TNNT1, DES, TRDN, MYH6, MYH11, and MYH13." (PMID 36378654, 2022). "This supposition seems reasonable since mutations in TNNI1 and TNNI2 are found in human cancer reported in online databases." (PMID 29416706, 2018). "Based on the prior study and observation of TNNI1 overexpression in cancer databases, the same group explored the potential link between ssTnI expression and cancer in a subsequent investigation." (PMID 29416706, 2018). "The correlations between TNNI1 expression levels and cancer type in these databases justify an experimental study to identify the underlying biology." (PMID 27437768, 2016). "The proven effectiveness of blocking Troponin I to restrain a diversity of tumor cell types may open the possibility to further consider this protein as a new anti-tumor agent in cancers where TNNI1 is overexpressed." (PMID 27437768, 2016). "Not all types of human cancer, however, show correlation with high TNNI1 expression (e.g.: squamous lung cancer)." (PMID 27437768, 2016).
tumor (3 papers, 2016 to 2021). "Elucidating the functional relevance of TNNI1 overexpression in aggressive brain tumors may provide a platform for developing novel therapies and diagnostic markers, and ultimately advance our understanding of tumor pathogenesis in the brain." (PMID 29416706, 2018). "It has been previously shown that expression of TNNI2 inhibits endothelial cell proliferation and angiogenesis (indicated by the T-bar), whereas expression of TNNC1 and TNNI1 promote tumor growth and metastasis (indicated by arrows)." (PMID 29416706, 2018). "In addition, we validated the fly results in mammals by analyzing the effects of down-expression of human TNNI1 in tumor growth of human xenografts in mice." (PMID 27437768, 2016). "Finally, the TNNI1 peptide and the TNNI1 shRNAi used here severely limited tumor growth." (PMID 27437768, 2016). "Seven different human tumor cell lines of various oncogenic origins and the non-oncogenic embryonic kidney cell line (HEK293T) as control were treated with a peptide corresponding to the 93-116 residues of human TNNI1." (PMID 27437768, 2016).
TNNI1 also shares sentences with these, for which no sentence is quoted: congenital myopathies (1 paper); dilated cardiomyopathy (1); endometrium (1); laryngeal carcinoma (1); lung adenocarcinoma (1); muscular dystrophies (1); myocarditis (1); myopathy (1); restrictive cardiomyopathy (1); stomach cancer (1).